TGIF1 (TGFB induced factor homeobox 1)
Diseases named in the same sentence as TGIF1 in open-access papers (continued):
Sharing a sentence is not in itself a finding about the gene and the disease.
tumor (26 papers, 2014 to 2026). "In BRC, the TGIF1 upregulation is associated with poor prognosis and promotes the Wnt1-driven tumor progression." (PMID 38067260, 2023). "IHC of serial sections revealed that high expressions of CRC (ELF3/EHF/TGIF1-High) were closely associated with high proliferative activity in tumor tissue and poor prognosis on patients with LUAD." (PMID 33070167, 2020). "Based on these reports, we hypothesized that TGIF1 deficiency or downregulation is an alternative mechanism underlying the late-stage TGFβ1/Smad-mediated tumor progression and metastasis." (PMID 31109321, 2019). "In order to investigate the molecular mechanism underlying the tumor-promoting function of TGIF1, we used reporter assays to screen the potential roles of TGIF1 in regulating various signaling pathways and identified TGIF1 as an important promoting factor of Wnt/β-catenin signaling pathway." (PMID 29050273, 2017). "Like ZEB1, TGIF1 was a potential hypermethylated biomarker identified in another tumor tissue type in this analysis." (PMID 38886487, 2024). "Collectively, the tumor suppressive activity of HDAC3 silencing was reproduced in vivo dependent on the miR-494/TGIF1/TGFβ axis." (PMID 35578338, 2022). "The results validated that down-regulation of HDAC3 or TGIF1, or up-regulation of miR-296-3p resulted in suppressed tumor growth, elevated apoptosis rate and inhibited TGF-β1, Smad2 and Smad3 expression." (PMID 33203425, 2020). "After depletion of HDAC3 or TGIF1 or augment of miR-296-3p, the tumor cells were characterized by cellular shrinkage, dense chromatin in the nucleus, markedly reduced mitotic division, with scattered foci and necrotic lesions fused into sheets." (PMID 33203425, 2020). "Among these proteins, PKNOX1 is also known to have tumor suppressor function and TGIF1 is reported to act as negative regulator in MLL-rearranged AML36." (PMID 32409701, 2020). "IHC revealed that expressions of ELF3, EHF and TGIF1 were higher in LUAD tumor tissues compared with peritumoral tissues." (PMID 33070167, 2020). "It is demonstrated that down-regulated HDAC3 or TGIF1 or up-regulated miR-296-3p is the restriction for tumor growth in nude mice." (PMID 33203425, 2020). "Restored miR-296-3p suppressed TGIF1 and reduced TGFβ pathway-related proteins, inhibited CRC proliferation, invasion, and migration in vitro and slowed down tumor growth and induction of apoptosis in vivo, which were reversed by TGIF1 overexpression." (PMID 33203425, 2020). "Accordingly, TGIF1 ablation significantly enhanced the formation of tumor colonies in soft agar, suggesting the increased anchorage-independent growth ability of PDAC cells upon TGIF1 loss." (PMID 31109321, 2019). "To further investigate the role of TGIF1 in tumor formation, we evaluated tumor-promoting functions of TGIF1 in the nude mice model." (PMID 29050273, 2017). "TGIF1 was degraded by the CRC tumor suppressor FBXW7 and enhanced TGFβ-dependent cell growth and migration." (PMID 26109429, 2015). "Furthermore, we observed that the TGIF1 protein level was increased in the CDR1as-overexpressing group of subcutaneous tumor tissues." (PMID 38067260, 2023). "Silencing of HDAC3 inhibited tumor growth of ESCC in vivo via the MiR-494/TGIF1/TGFβ axis." (PMID 35578338, 2022). "Hence, the study is intended to probe into the mechanism translation of HDAC3, miR-296-3p, TGFβ signaling pathway and TGIF1 in CRC and it is elucidated that HDAC3 deteriorates CRC progression and promotes tumor growth via miR-296-3p/TGIF1/TGFβ axis." (PMID 33203425, 2020). "TGIF1 is a transcriptional co-repressor which exerts as a tumor promoter of CRC exacerbation." (PMID 33203425, 2020). "Supporting our hypothesis, bioluminescence imaging revealed a decreased number of bone metastases in the long bones of Tgif1−/− mice compared to control littermates (28.26% vs. 48.89%, respectively) 7 days after tumor cell injection." (PMID 32272947, 2020).
tumor (continued). "Meanwhile, the tumor sphere formation assays also demonstrated that TGIF1 loss significantly increased the tumor sphere-forming ability of PDAC cells with or without TGFβ1 treatment." (PMID 31109321, 2019). "Collectively, our results imply that TGIF1 may play a role in the regulation of PD-1/PD-L1 signaling axis of the tumor microenvironment, thereby influencing pancreatic tumorigenesis." (PMID 31109321, 2019). "Furthermore, tumor SCID or allogeneic graft studies revealed that TGIF1 inactivation resulted in increased tumor incidence and size (Fig. 5Gi-ii)." (PMID 31109321, 2019). "Taken together, our findings indicate that TGIF1 promotes tumor formation in vivo." (PMID 29050273, 2017). "Moreover, mRNA levels of the Wnt target genes CCND1, AXIN2 and c-Myc were dramatically decreased in the tumor with low TGIF1 levels." (PMID 29050273, 2017). "However, levels of Klf5 and Tgif1 were elevated in R482Q/+;1322T compared with 1322T tumours (p=0.045 and p=0.042, respectively, t test), consonant with the findings in normal intestinal epithelium." (PMID 23676439, 2014). "Emerging evidence exhibits that CDC4 has been confirmed as a tumour suppressor due to the wide involvements in degradation of diverse proteins associated with oncogenic developments, including cyclin E, c-Myc, c-Myb, c-Jun, Notch, MCL1, MED13/13L, PGC-1α, C/EBPα, TGIF1 and KLF5." (PMID 40260685, 2025). "Therefore, a conclusion could be drawn that the anti-tumor action of miR-494 in ESCC relied on TGIF1 downregulation." (PMID 35578338, 2022). "Deciphering the molecular mechanisms highlighted the TGIF1 loss-induced activation of the hyaluronan synthase 2 (HAS2)-CD44 signaling pathway and upregulation of the immune checkpoint regulator PD-L1 to facilitate the epithelial–mesenchymal transition (EMT) and tumor immune suppression." (PMID 31109321, 2019). "Next, we investigated the effects of TGIF1 deficiency on leukocyte infiltrations in the tumor microenvironment; IHC and flow cytometry (FACS) analyses were employed to determine the numbers of leukocytes in the stromal tumor microenvironment of the PKTP mice compared with that of the PKP model." (PMID 31109321, 2019). "Furthermore, our data revealed the role of TGIF1 in regulating TGFβ-induced hyaluronan synthase 2 (HAS2) activity, which has a profound effect on tumor-associated macrophage (TAM) polarization; moreover, TGIF1 exhibits an antitumor immunity potential through the suppression of PD-L1 expression." (PMID 31109321, 2019). "Based on the observations of the histological and glucose tolerance examinations in the pancreas of the Pdx-1CreTGIF1L/L mice (N = 16), we proposed that pancreas-specific TGIF1 deficiency does not lead to any pancreas developmental defect or result in neoplasms." (PMID 31109321, 2019). "It was observed that tumor weight was much lighter and tumor growth speed was slower in the presence of sh-HDAC3, which was negated by oe-TGIF1 treatment." (PMID 35578338, 2022). "FBXW7 is a tumor suppressor and regulates the TGF-β/BMP-pathway by targeting for degradation co-repressor TGF-β-induced factor 1 (TGIF1), which recruits specific repressor complexes to SMAD2." (PMID 35805024, 2022). "It has been revealed that TGIF1 is abnormally high-expressed in LUAD tissues, and this is closely related to a high proliferative activity of tumor tissues and poor prognosis of patients with LUAD." (PMID 35668494, 2022). "This study illustrates that down-regulation of HDAC3 or TGIF1 or up-regulation of miR-296-3p discourages CRC cell progression and slows down tumor growth, which guides towards a novel direction of CRC treatment." (PMID 33203425, 2020). "TGIF1 and TGIF2 that are repressors of tumor suppressor SMAD proteins are also differentially methylated." (PMID 28423671, 2017).
tumor (continued). "With integrative analysis of whole genome CRISPR screening data from DepMap Project, GBC RNAseq data, and the Coltron prediction results, five CRC TFs (SOX9, TCF7L2, FOXA1, TGIF1 and HES1) were found to meet all our defined criteria for gene expression and tumor‐dependency levels." (PMID 39492805, 2024). "Previous studies have shown that elevated TGIF1 in triple‐negative breast cancer can promote malignant progression of the tumor and shorten the patients' survival." (PMID 35569122, 2022). "Remarkably, ELF3, EHF, and TGIF1 were highly expressed in LUAD tumor tissue compared with normal lung tissue, and the high expression of these TFs were positively correlated with poor prognosis in LUAD patients." (PMID 33070167, 2020). "On the whole, the present study has pictured the mechanisms of HDAC3, TGIF1, TGFβ signaling pathway and miR-296-3p in CRC that knockdown of HDAC3 or TGIF1 or up-regulation of miR-296-3p blocks CRC development and tumor growth via inhibiting TGFβ signaling pathway." (PMID 33203425, 2020). "Depleted HDAC3 elevated miR-296-3p expression and reduced TGIF1 expression, decreased TGFβ pathway-related proteins, inhibited CRC proliferation, invasion, and migration in vitro and slowed down tumor growth and induction of apoptosis in vivo, which were reversed by miR-296-3p knockdown." (PMID 33203425, 2020). "TGIF1 knockdown inhibits WNT target genes and in vitro cell invasion suggesting that TGIF1 might be a key target of the SID decoys to block tumor invasion." (PMID 29179446, 2017). "Additionally, owing to the scarcity of literature on the relationship between HDAC3 and TGIF1, further investigation is still required so as to validate the established promoting effect of HDAC3 on ESCC cell malignant phenotypes and tumor growth through blockade of miR-494-mediated TGIF1 inhibition." (PMID 35578338, 2022). "Furthermore, immunohistochemistry and HE staining showed that the expression of Ki67 and tumor cells in nude mice were diminished in the presence of sh-HDAC3, the results of which could be reversed by further oe-TGIF1 treatment." (PMID 35578338, 2022).
infection (2 papers, 2019 to 2023). The state of being infected such as from the introduction of a foreign agent such as serum, vaccine, antigenic substance or organism. "Here, we detected the downregulation of TGIF1 as early as 1 week post-infection." (PMID 31555289, 2019). "Among critical inflammation and immune response biomarkers, HSP100, TNF-α, TGIF-1, TGIF-2, mCCL22, iNOS, caspase-1, and caspase-8 were significant at different time points in the infection-derived EVs during CCoV infection of CRFK cells." (PMID 36979955, 2023).
diseases of the central nervous system (1 paper, 2022). "TGIF1 is expressed in the fetal and adult nervous system, and its deletions have been related to diseases of the central nervous system." (PMID 35331298, 2022).
TGIF1 also shares sentences with these, for which no sentence is quoted: colorectal tumor (2 papers); Thrombocytopenia (2); Thrombocytosis (2); thrombosis (2); atrial fibrillation (1); cervical cancer (1); chronic otitis media (1); cystic fibrosis (1); depression (1); diabetes insipidus (1); diabetic cardiomyopathy (1); enteropathy (1); esophageal cancer (1); esophageal squamous cell carcinoma (1); hemochromatosis (1); Intellectual disability (1); liver fibrosis (1); lung adenocarcinoma (1); lung disease (1); melanoma (1); oligodendroglioma (1); ovarian carcinoma (1); pulmonary fibrosis (1); Radiation-Induced Intestinal Injury (1); scleroderma (1); thyroid cancer (1); triple-negative breast carcinoma (1).